SNORA40B (small nucleolar RNA, H/ACA box 40B)
Gene: Small nucleolar RNA gene on chromosome 2 (135,136,628 to 135,136,755, forward strand). Ensembl gene ENSG00000208308.
Gene Ontology:
Biological process: RNA processing
Cellular component: nucleolus
Homologues: Orthologues: chimpanzee SNORA40B (100% identical), macaque SNORA40B (98% identical). Paralogues in human: SNORA40 (97% identical), SNORA40C (95% identical).